LINC01965 (long independently transcribed non-coding RNA 1965)
Gene: Long non-coding RNA gene on chromosome 2 (103,873,876 to 104,101,974, forward strand). Ensembl gene ENSG00000256637.
Diseases named in the same sentence as LINC01965 in open-access papers:
LINC01965 is named in the same sentence as 1 disease in open-access papers, as found by Europe PMC text mining. Sharing a sentence is not in itself a finding about the gene and the disease.
LINC01965 shares sentences with these, for which no sentence is quoted: Alzheimer disease (1 paper).